BCL2 (BCL2 apoptosis regulator)
Diseases named in the same sentence as BCL2 in open-access papers (continued):
Sharing a sentence is not in itself a finding about the gene and the disease.
tumor (continued). "It is thus possible that BCL2 expression in primary tumor and bone metastasis could be predictive of taxane treatment response." (PMID 32685011, 2020). "These tumor cells sharetrisomy 12 as a common genetic abnormality, and it is speculated that trisomy 12 may have occurred earlier than BCL2 and BCL6 translocations." (PMID 35847735, 2020). "The Bcl-2/Bax ratio increased in the control group on the second day, and decreased in the other three groups, thereby indicating that the IS had a significant cytotoxic effect on tumor cells." (PMID 32929372, 2020). "Finally, we detected the level of Bcl-2 family anti-apoptotic protein Bcl-2, Bcl-XL, Mcl-1, and Survivin, these proteins were overexpressed in tumor cells and helped tumor cells avoid apoptosis." (PMID 31569691, 2019). "Additionally, along with cisplatin, infection of CRAd also triggers the transcription of apoptotic cascade proteins (bax, bcl-2, caspase-3) resulting in enhanced tumor selective apoptotic killing." (PMID 30841620, 2019). "Bcl-2 may thus be tumor-suppressive and at the same time oncogenic in specific cell types or under specific circumstances." (PMID 30630524, 2019). "In vitro and in vivo anti-tumor effects revealed that siRNA/DOX/GH-DPP nanoparticles could suppress the expression of Bcl-2 gene, enhanced cell apoptosis, and exhibited higher anti-tumor effect." (PMID 30723405, 2019). "Furthermore, the combined treatment maximized the percentage ratio of Bax to Bcl-2 protein expression in tumor cells." (PMID 31504707, 2019). "They found that Bcl-2 was involved in the tumor pathogenesis by inhibiting apoptosis." (PMID 30956677, 2019). "Notably, Bcl2 is a direct target of miR-139 and the anti-tumor efficacy of miR-139 administration is mediated via Bcl2 suppression in CRC." (PMID 31426807, 2019). "We demonstrated that CREB3 could bind to the promoter of c-Jun and subsequently enhance the expression of mmp9, an important biomarker for tumor metastasis, and Bcl-2, a pivotal antiapoptotic molecule in the plasma." (PMID 30940151, 2019). "In addition, the increased cell survival due to overexpression of Bcl-2 has been shown to contribute to tumor development and resistance to various anti-cancer therapies." (PMID 31143550, 2019). "Moreover, immunoblotting analysis was performed to detect the levels of the proliferation (PCNA) marker and anti‐apoptosis marker (Bcl‐2) in xenograft tumour tissues." (PMID 31483572, 2019). "Further experiments demonstrated that the ectopic expression of miR-3188 could suppress tumor cell growth and induce apoptosis by targeting BCL2 both in vitro and in vivo." (PMID 30961650, 2019). "Of the 58 tumor samples 9 (15.5%) cases showed high Bcl-2 expression (Bcl-2H)." (PMID 31766723, 2019). "Another study identified a population of nurse-like cells in the TME of CLL that had a protective effect on ibrutinib-induced tumor cell apoptosis, which could be partially attributed to the inactivation of natural Bcl-2 antagonist in nurse-like cells." (PMID 30927928, 2019). "Expression of BCL-2 was low in all normal and tumor tissue from the oral cavity and hypopharynx, whereas it appeared to be more highly expressed in the tumor core, advancing front and in the adjacent normal tissues of the larynx." (PMID 31801952, 2019). "The difference in the susceptibility of D-10-0021 MG, DM440, and SUM159-R113 cells to the 9.2.27-PE38KDEL, ABT combinations impelled us to examine the role of selected prosurvival (Bcl-xL and Mcl-1) and proapoptotic (Bim and Bax) Bcl-2 members in potentiating tumor cell death." (PMID 30625226, 2019).
tumor (continued). "The induction of tumor cell apoptosis through the downregulation of cyclin E expression and upregulation of p21 expression, which causes G1 arrest in HEY and SKOV3 cells and downregulates Bcl-2 protein expression and upregulates Bax protein expression." (PMID 30837865, 2019). "The in vivo xenograft experiment showed that Ls significantly inhibited the tumor growth, which may be through down-regulation the protein expression of Bcl-2 and Bak, up-regulation the protein expression of Bax and Caspase-3." (PMID 31299960, 2019). "Besides, knockdown of miR-196a and miR-196b led to obvious decrease of Bcl-2 protein level and increase of Bax protein abundance in xenograft tumor tissues." (PMID 30988277, 2019). "The results suggested that the anticancer molecular mechanism of the combination therapy of glycyrrhizin and doxorubicin in ALG NGPs was performed via regulating apoptosis pathway of Bax/Bcl-2 ratio and caspase-3 activity, which was also verified in H22 tumor-bearing mice." (PMID 31534548, 2019). "Recent developments allow changes in the Bcl-2 protein landscape of tumours to be exploited." (PMID 31681471, 2019). "Furthermore, western blotting and an immunohistochemistry assay showed that the levels of Caspase-3, Caspase-8 and Bax in the tumor tissues were significantly increased, while the level of Bcl-2 decreased in a dose-dependent manner." (PMID 30651572, 2019). "Among numerous miRNAs, miR-15/16 can directly target BCL-2 and function as a tumor suppressor." (PMID 31462894, 2019). "The anti-tumour mechanism of drug-drug combination is to induce apoptosis through up-regulating the activity of caspase-3 and caspase-9 by inhibiting the activity of bcl-2." (PMID 30872765, 2019). "Furthermore, combined suppression of XPO1 and BCL2 synergizes to induce massive cell death in DHL tumor cells in vitro." (PMID 31752970, 2019). "Moreover, Bcl-2 is known as a tumor suppressor, which inhibits apoptosis and promotes cell survival." (PMID 30627053, 2019). "Therefore, it is urgent to develop novel Bcl-2 anti-apoptotic proteins inhibitors with excellent anti-tumor activity and little side effects." (PMID 31057406, 2019). "The expressions of Bax, Bcl-2 and caspase 3 in tumor cells were gauged using QPCR." (PMID 31426614, 2019). "It has been shown that GPx may inhibit apoptosis by removing hydroperoxides, or by alternating Bax/Bcl-2 ratio, which may occur as a relatively early event in tumor development." (PMID 30978928, 2019). "The tumor morphology and Bcl-2 status were evaluated by immunohistochemistry in each case." (PMID 31754362, 2019). "Moreover, CCL9 increases the levels of phosphorylated protein kinase B (p-PKB) and B-cell lymphoma-2 (Bcl-2) in tumor cells, which promote the survival of newly arriving tumor cells in the PMN." (PMID 30792719, 2019). "Bax proteins are expressed in all tumor cells, but their function is inactivated by Bcl-2 proteins." (PMID 31123430, 2019). "Likewise, a significant prevention of the in vivo growth of therapeutic-resistant H460/Bcl-2 tumor was observed as a consequence of the sustained release of supramolecular hydrogel and targeting ability mediated by FA ligand." (PMID 30960498, 2019). "Drawing from the tumor immunoediting literature, we identified overexpression of the pro-survival protein BCL-2 as one potential mechanism of resistance—which can act to antagonize perforin/granzyme killing by sequestering truncated BH3-only domain members of the BCL-2 family." (PMID 31447850, 2019). "Moreover, previous data showed that BV acts as an anti-cancer agent through apoptosis, necrosis, and lysis induction of tumor cells via the activation of several signaling pathways involving a Bcl-2 protein, caspase 3, in synovial fibroblasts." (PMID 30935025, 2019).
tumor (continued). "Similarly, miR-34a, another miRNA found to be differentially expressed in drug resistant cells in this study, was also demonstrated to promote apoptosis and enhance tumour cell response via pathways involving BCL2 repression." (PMID 35582270, 2019). "In conclusion, the present study determined that the use of drug-loaded microbubbles combined with ultrasound may effectively inhibit tumor growth by promoting the apoptosis of cancer cells via regulation of Bax and Bcl-2 expression." (PMID 30578377, 2019). "According to this information, it may imply that Bcl-2 overexpression is related to tumor progression and tumor survival factor in tumor cells." (PMID 31620453, 2019). "We observed that only the Bcl-2 inhibitor (ABT-737) was able to significantly inhibit cell invasion, demonstrating the importance of Bcl-2 in the process of tumor cell invasion and indicating that ABT-737 may be a good strategy to restrain invasion." (PMID 31759362, 2019). "However, to our surprise, none of the DHL cell lines was resistant to both, lending experimental support to the combinatorial use of XPO1 and BCL2 inhibitors to eradicate DHL tumor cells." (PMID 31752970, 2019). "However, it had been found that some tumor cells over-expressed anti-apoptotic protein Bcl-2 and antagonized the IL-24 function." (PMID 31781493, 2019). "Moreover, TMEA upregulated the expression of proapoptotic factors Bax and caspase-3 and downregulated the expression of antiapoptotic factors CD31 and Bcl-2 in cancer cells and/or tumor tissues." (PMID 32047442, 2019). "Moreover, we found that Bcl-2 expression was decreased, whereas the expression levels of Bax and cleaved caspase-3 were increased in the tumor tissues of vitexin-treated mice." (PMID 30797236, 2019). "Furthermore, the expression level of the apoptotic gene Bax was significantly increased, while the expression level of Bcl-2 was decreased in tumor tissues treated with PTX plus UA compared with the expression levels of cells treated with PTX only." (PMID 31259152, 2019). "To gain insights into the underlying mechanism of apoptosis induction effect caused by Huaier (6 mg/ml), 5-FU (30 μg/ml), and their combination, we detected the expressions of two anti-apoptotic protein Mcl-1 and Bcl-2, which were considered a therapeutic target in tumor apoptosis process." (PMID 31391034, 2019). "Downregulation of the death suppressor bcl-2 and activation of caspase-8 and bax could inhibit tumor growth through promoting apoptosis." (PMID 31118873, 2019). "D-M-EXOs could dramatically inhibit tumor growth and up-regulate apoptosis in H22 cells by decreasing Bcl-2 expression and increasing Caspase-3 expression." (PMID 31695794, 2019). "As the two common drivers of DHL, MYC and BCL2 cooperate in lymphomagenesis and tumor maintenance." (PMID 31752970, 2019). "Similarly, exposure of cells and tumours with USMB in vivo and in vitro have demonstrated enhanced tumour inhibition via regulation of Bax and Bcl-2 along with increased expression of cell-death related caspase-3, cleaved caspase-3, and caspase-8." (PMID 31851698, 2019). "Effects were additive for ING4 and IL-24, and in addition up-regulation of the tumor suppressors p21, p27, fas cell surface death receptor (Fas), Bax, and the apoptosis-promoting cleaved caspases-8, -9, -3, and down-regulation of the tumor-promoter Bcl-2 apoptosis regulator (Bcl-2) was observed." (PMID 31390718, 2019). "The Bcl-2 protein is situated in the mitochondrial inner membrane and suppresses intrinsic apoptosis through arresting the cell in the G0/G1 phase of the cell cycle to prolong the survival of the tumor cell." (PMID 31123430, 2019). "They found that this new nanoparticle loaded with CPT had enhanced tumor accumulation, induced apoptosis, and efficiently downregulated Bcl-2 mRNA expression, which was deemed to promote apoptosis and inhibit tumor growth in orthotopic colon tumors in mice in vivo." (PMID 31346334, 2019).
tumor (continued). "Furthermore, the anti-tumor effects were induced through binding of secreted Ac-APE1/Ref-1 to RAGE, which caused ROS generation, increased Bax/Bcl-2 ratio, and caspase activation." (PMID 29880821, 2018). "Furthermore, VEGF-A promotes survival in both tumor and endothelial cells and prevents apoptosis via inducing BCL-2." (PMID 30239898, 2018). "Agonist (clofibrate) significantly decreased Bcl2 protein levels and increased autophagy and inhibition of tumor progression in a PPARα-dependent manner, which suggests that PPARα could be a potential drug target for cancer treatment." (PMID 30519260, 2018). "In the Western blot experiments, the tumor tissues in the OA‐treated group had a significant increase in the protein level of Bax/Bcl‐2, cleaved caspase 3 and cleaved PARP than did the control group, indicating increased apoptosis in tissues in the OA‐treated group." (PMID 29533007, 2018). "Moreover, numerous genes modified by m6A have been revealed to play regulatory roles in tumour formation, such as BCL2, PTEN, SOCS2, FOXM1 and HBXIP." (PMID 30031372, 2018). "Furthermore, we demonstrate that combined inhibition of two miR‐15/16 targets, FGFR1 and Bcl‐2, has synergistic effects on tumor cell growth encouraging further consideration as novel combination strategy in MPM." (PMID 29094504, 2018). "In vivo, S55746 is highly efficacious against BCL-2 dependent tumor models without causing platelet loss, in agreement with its strong selectivity for BCL-2 over BCL-XL, thus supporting its evaluation in clinical trials." (PMID 29732004, 2018). "CD34 and Bcl-2 expression rates were lower in higher grade tumours." (PMID 30183767, 2018). "In addition, immunohistochemical data indicates that, at least in part, FAM3B promotes tumorigenicity in these cells by the upregulation of Bcl-2 and downregulation of Bax, with a high correlation between tumor growth and FAM3B/Bcl-2 gene expression." (PMID 29357840, 2018). "Thus, it would be of interest to further analyse the molecular mechanisms behind Bcl-2 intracellular distribution in tumor cells." (PMID 29497611, 2018). "Moreover, the molecules such as p-ERK, p-AKT, and Bcl-2 in tumor tissues were all down-regulated, whereas Bax was up-regulated in response to trimebutine treatment, which was consistent with in vitro results we observed." (PMID 29977208, 2018). "In addition, we found that 17-AAG had a combined effect in the downregulation of HDAC1, HDAC2, the anti-apoptotic gene BCL-2 and tumour survival gene STAT3 in Hep3B cells in combination with Resminostat." (PMID 30035186, 2018). "Moreover, it was found that treatment with Bcl-2-silencing plasmid efficiently down regulated the expression of Bcl-2 gene in tumor cells and induced their apoptosis ratio remarkably." (PMID 29861465, 2018). "We further detected the relationship of PPARα/Bcl2/autophagy signaling on tumor progression." (PMID 30519260, 2018). "Conversely, oncogenes, including Akt, mTOR and Bcl-2, inhibit autophagic processes indicating that elevated autophagy signaling may contribute to tumor suppression." (PMID 29329543, 2018). "Might potent BCL-2 inhibition lead to reductions or enrichments in tumor-infiltrating immune cells such as dendritic cells, natural killer cells, myeloid derived suppressor cells, and various B- and T-cell populations?" (PMID 30406027, 2018). "It is conceivable that targeting the pro-survival BCL-2 proteins could help eliminate pre-cancerous lesions or early-stage tumours." (PMID 29769323, 2018).
tumor (continued). "The expression of pro-apoptotic proteins FasL and Bax and anti-apoptotic protein Bcl-2 were examined in mice under different treatment conditions: normal control skin, tumor skin alone, and yeast-treated (100 μl) tumor skin at concentrations 107, 108, and 109 cells/ml." (PMID 31098389, 2018). "Thus, Bcl-2-siRNA treating mice group had three-fold reduction of tumor volume and weight in comparison to control group and significant lower tumor growth rate relative to control group." (PMID 29861465, 2018). "Additionally, ANRIL induces tumor cell proliferation by up-regulating the expression of Bcl-2 and down-regulating P15INK4B expression in epithelial ovarian cancer." (PMID 29581867, 2018). "The tumor Bax and Bcl-2 levels were determined via western blotting." (PMID 30564277, 2018). "Bcl-2 protein is an endometrial protein, mainly localized in mitochondria, endoplasmic reticulum membrane and the nuclear membrane, and is present in a variety of tumor cells." (PMID 30092797, 2018). "Because BCL-2 plays such an important role in the development and shaping of the immune system it will also be interesting to explore how venetoclax may impact tumor microenvironments." (PMID 30406027, 2018). "Moreover, oridonin dose-dependently increased the ratio of Bax/Bcl-2 and the cleavage of Caspase-3 and Caspase-9 in tumor tissues." (PMID 29323103, 2018). "(v) Bcl2 protein expression, because it was surprisingly shown that low Bcl2 levels were correlated with an increase in the number of relapses in stage II CRC, and high levels of Bcl2 protein seem to be associated with slower local tumor growth." (PMID 29743633, 2018). "An imbalance between antiapoptotic proteins, such as Bcl-2 and Bax, can induce dysregulation of apoptosis (programmed cell death), which may lead to oncogenesis and tumour development." (PMID 29476674, 2018). "Similarly, lack of bcl-2 expression was correlated with increased relapses while bcl-2 immunodetection was accompanied by slower local tumor growth." (PMID 29850390, 2018). "However, when stably coexpressed, myc and Bcl-2 can cooperate to increase tumor incidence in a variety of lymphoid and epithelial cell types as well as transgenic models." (PMID 30026762, 2018). "To detect Bcl-2 expression at the tumor site, we performed immunofluorescence on colon slides." (PMID 30235866, 2018). "However, gallic acid is believed to exhibit its anticancer effect by upregulating Bax and downregulating Bcl-2 in other tumour models." (PMID 29568751, 2018). "Thus, we conclude that FAM3B-mediated upregulation of Bcl-2 anti-apoptotic family members can contribute to apoptosis inhibition and, consequently, increased of tumor growth in mice xenotransplanted with DU145 cells." (PMID 29357840, 2018). "In addition, the Bcl-2 expression in BAP1 tumor cells isolated from mice were reduced compared to the control cells in line with the elevated number of cleaved caspase-3 cells observed in BAP1 expressing tumor cells." (PMID 29686263, 2018). "Furthermore, Glaucocalyxin A dose-dependently increased the ratio of Bax/Bcl-2 and the cleavage of caspase-3 and caspase-9 in tumor tissues." (PMID 29899333, 2018). "A decrease in Bcl2 expression was detected post treatment with 100 μl yeast concentration of 107 (P≤0.01), and the effect became highly significant at concentrations of 108 and 109 cells/ml in comparison to tumor skin homogenate (P≤0.001)." (PMID 31098389, 2018). "When The Bcl-2/Bax ratio decreased, it can induce the necrosis and apoptosis of tumor cells." (PMID 30402472, 2018). "Notably, the co-treatment of Caki-1 xenograft mice with 5-aza-2′-deoxycytidine and VBL led not only to suppression of tumor volume and weight but also reduced the expression of P-gp, Bcl-2 and cyclin B1." (PMID 29706891, 2018).